SPDYE4 (speedy/RINGO cell cycle regulator family member E4)
Tractability: No criterion of Open Targets' tractability assessment is met for any kind of drug.
Gene: Protein-coding gene on chromosome 17 (8,747,524 to 8,758,559, reverse strand). Ensembl gene ENSG00000183318.
Gene Ontology:
Molecular function: protein binding; protein kinase binding
Genetic constraint (gnomAD): Loss-of-function variants: 30 observed, 35.78 expected, observed/expected ratio (o/e) 0.84, 90% interval 0.63 to 1.14. The upper end of that interval is the gene's LOEUF score, 1.14, which puts it in group 4 of 6, group 1 being the genes least tolerant of losing a copy. Missense variants: 300 observed, 310.25 expected, observed/expected ratio (o/e) 0.97, 90% interval 0.88 to 1.06. Synonymous variants: 131 observed, 118.41 expected, observed/expected ratio (o/e) 1.11, 90% interval 0.96 to 1.28.
Homologues: Orthologues: chimpanzee SPDYE4 (97% identical), macaque SPDYE4 (92% identical), rat Spdye4 (62% identical), mouse Spdye4a (61% identical), mouse Spdye4b (55% identical). Paralogues in human: SPDYE16 (71% identical), SPDYE3 (70% identical), SPDYE18 (70% identical), SPDYE21 (70% identical), SPDYE5 (70% identical), SPDYE2 (69% identical), SPDYE2B (69% identical), SPDYE6 (69% identical), SPDYE10 (68% identical), SPDYE11 (68% identical), SPDYE12 (68% identical), SPDYE13 (68% identical), and 6 more.
Diseases named in the same sentence as SPDYE4 in open-access papers:
SPDYE4 is named in the same sentence as 1 disease in open-access papers, as found by Europe PMC text mining. Sharing a sentence is not in itself a finding about the gene and the disease. The quoted sentences say what the papers report.
tumor (1 paper, 2021). "Putative GPR15 co-expressed genes, such as TACR1, TAS2R9, SPDYE4, or GPR182, could be a more specific sign for tumor cells of adenocarcinoma or for healthy epithelial cells from which the tumor originates since all four genes were not expressed in GPR15+CD3+ lymphocytes." (PMID 34639163, 2021).